TMX2 (thioredoxin related transmembrane protein 2)
Description:
Endoplasmic reticulum and mitochondria-associated protein that probably functions as a regulator of cellular redox state and thereby regulates protein post-translational modification, protein folding and mitochondrial activity. Indirectly regulates neuronal proliferation, migration, and organization in the developing brain.
Synonyms: TXNDC14; CGI-31; PIG26; PDIA12; NEDMCMS
Tractability: Antibody: UniProt predicts a signal peptide or a membrane-spanning region. PROTAC: ubiquitination databases record sites on it; its protein half-life has been measured.
Safety:
Unwanted effects reported when the protein is acted on. In parentheses: how it was acted on, where the effect was seen, and who reports it.
alcoholism (source: ClinPGx)
Gene: Protein-coding gene on chromosome 11 (57,712,562 to 57,742,987, forward strand). Ensembl gene ENSG00000213593.
Subcellular location: Endoplasmic reticulum membrane; Mitochondrion membrane
Subcellular location (Human Protein Atlas): Cytosol; Nucleoplasm
Gene Ontology:
Molecular function: disulfide oxidoreductase activity; identical protein binding; protein binding
Biological process: brain development; regulation of mitochondrion organization
Cellular component: endoplasmic reticulum membrane; mitochondria-associated endoplasmic reticulum membrane contact site; mitochondrial membrane; mitochondrion
Genetic constraint (gnomAD): Loss-of-function variants: 24 observed, 38.96 expected, observed/expected ratio (o/e) 0.62, 90% interval 0.44 to 0.87. The upper end of that interval is the gene's LOEUF score, 0.87, which puts it in group 3 of 6, group 1 being the genes least tolerant of losing a copy. Missense variants: 340 observed, 385.19 expected, observed/expected ratio (o/e) 0.88, 90% interval 0.81 to 0.97. Synonymous variants: 166 observed, 148.37 expected, observed/expected ratio (o/e) 1.12, 90% interval 0.99 to 1.27.
Homologues: Orthologues: chimpanzee TMX2 (99% identical), macaque TMX2 (98% identical), dog TMX2 (96% identical), rabbit TMX2 (96% identical), pig TMX2 (93% identical), rat Tmx2 (93% identical), mouse Tmx2 (93% identical), guinea pig TMX2 (88% identical), tropical clawed frog tmx2 (77% identical), zebrafish tmx2b (73% identical), Drosophila melanogaster CG11007 (39% identical), Caenorhabditis elegans C35D10.10 (32% identical).
Diseases named in the same sentence as TMX2 in open-access papers:
TMX2 is named in the same sentence as 17 diseases in open-access papers, as found by Europe PMC text mining. Sharing a sentence is not in itself a finding about the gene and the disease. The quoted sentences say what the papers report.
hepatocellular carcinoma (4 papers, 2023 to 2025). A malignant tumor that arises from hepatocytes. "Additionally, TMX2 has been implicated in tumor biology, where it promotes cell survival and contributes to chemotherapy resistance in hepatocellular carcinoma." (PMID 40497397, 2025). "To further investigate the biological roles of TMX2 knock-down on invasion and migration of hepatoma cell lines (HepG2 and Huh-7), we also transfected shRNA plasmid targeting TMX2 into cells to knockdown endogenous TMX2." (PMID 38147024, 2023). "Previous studies have reported that TMX2 promotes hepatocellular carcinoma (HCC) growth and suppresses apoptosis." (PMID 40497397, 2025). "TMX2 enhances hepatocellular carcinoma (HCC) cell viability by promoting autophagy and mitophagy, is upregulated in HCC tissues, associated with poor prognosis, and potentially serves as a therapeutic target." (PMID 39315094, 2024).
microcephaly (3 papers, 2020 to 2025). A congenital or acquired developmental disorder in which the circumference of the head is smaller than normal for the person's age and sex. "TMX2 is associated with increased risk of neurodevelopmental disorders with microcephaly, cortical malformations, spasticity and congenital nervous system abnormalities." (PMID 40360802, 2025). "This includes a variant in TMX2 in case 19DG2556 with microcephaly and lissencephaly, which represents an independent confirmation of the very recently described TMX2-related disorder." (PMID 32552793, 2020). "Biallelic variants in thioredoxin-related transmembrane 2 protein (TMX2) can cause a malformation of brain cortical development characterized by microcephaly, polymicrogyria and pachygyria by an unknown mechanism." (PMID 40891441, 2025).
glioma (2 papers, 2020). A benign or malignant brain and spinal cord tumor that arises from glial cells (astrocytes, oligodendrocytes, ependymal cells). "Unlike previous findings, within the CGGA LGGGBM cohort, TMX2 was up-regulated in gliomas with mutant IDH and the expression of TMX4 in the two groups was not statistically significant." (PMID 32023222, 2020).
breast carcinoma (1 paper, 2007). "Our findings that PLD1 is overexpressed in TMX2-28 breast cancer cells and in a subset of breast tumours are consistent with the published data." (PMID 17726467, 2007).
cerebellar malformation (1 paper, 2025). Cerebellar malformations are diverse congenital anomalies frequently associated with developmental disability. "Recent studies have identified missense mutations in TMX2 associated with aberrant brain development and cerebellar malformations, highlighting its potential importance in developmental processes." (PMID 40497397, 2025).
epithelial dysplasia (1 paper, 2018). "When Grhl2 was knocked out 4 weeks into 4-NQO treatment (Tmx2), the epithelium developed multifocal mild to moderate epithelial dysplasia with a higher mitotic index." (PMID 29735981, 2018).
female infertility (1 paper, 2025). Diminished or absent ability of a female to achieve conception. "This study elucidates the expression pattern and functional role of Tmx2 in preimplantation mouse embryos, identifying it as a potential candidate gene associated with female infertility." (PMID 40497397, 2025).
Headache (1 paper, 2022). Cephalgia, or pain sensed in various parts of the head, not confined to the area of distribution of any nerve. "Of the genes at these loci, six (FAF1, TMX2-CTNND1, AARSD1, PLCD3, ZNF652, and C20orf203; headache-TSH) and six (HMGB1P45, RPL30P1, ZNF462, TMX2-CTNND1, ITPK1, SECISBP2L; headache-fT4) were significant in our gene-based analysis (pFisher’s combined p-value < 2.09 × 10−6)." (PMID 36672757, 2022).
liver cancer (1 paper, 2023). An epithelial or non-epithelial malignant neoplasm that arises from the liver. "In addition, TMX1, TMX2, and TMX3 are highly expressed in liver cancer cell lines, while TMX4 expressed is upregulated in melanoma cell lines." (PMID 38147024, 2023).
schizophrenia (1 paper, 2024). A major psychotic disorder characterized by abnormalities in the perception or expression of reality. "We observed two genes associated with schizophrenia: TMX2-CTNND1 (SNV20673) and CTNND1 (rs35542507, rs41277477, and rs73165153)." (PMID 38219215, 2024).
tumor (3 papers, 2022 to 2025). "By analyzing the actual protein expression in human tumor tissues, we found that the TMX2 protein is more strongly expressed in tumor tissues compared to adjacent normal tissues." (PMID 38147024, 2023). "TMX2 interference attenuates mitochondrial respiration, leading to enhanced aerobic glycolysis, which promotes tumor cell growth." (PMID 38147024, 2023).
cancer (2 papers, 2023 to 2024). A tumor composed of atypical neoplastic, often pleomorphic cells that invade other tissues. "In contrast, TMX2 was detrimental roles in different human cancers, including BLCA (p = 0.0093), BRCA (p = 0.026), HNSC (p = 0.012), LIHC (p = 0.0026), LUAD (p = 0.0028), and UVM (p = 0.0021)." (PMID 38147024, 2023). "By estimating StromalScore and ImmuneScore in TME, we found that TMX1, TMX3, and TMX4 exhibited a positive correlation with StromalScore and StromalScore in most cancer types, while TMX2 expression was negatively correlated with StromalScore and ImmuneScore." (PMID 38147024, 2023). "The inhibition of TMX2 expression decreased cell proliferation of breast cancer and also resulted in a reduction in the expression of genes related to the survival, differentiation, and metastasis of cancer cells." (PMID 38147024, 2023). "In this study, based on TCGA and GTEx databases, we analyzed the expression of TMX family (TMX1, TMX2, TMX3, and TMX4) genes in 23 different cancer types." (PMID 38147024, 2023). "To gain a better understanding of the biological mechanism of TMX family genes in cancers, we conducted KEGG signaling pathway enrichment analysis on TMX family genes (TMX2 and TMX4) with different expression phenotypes in KIRC and LIHC, respectively." (PMID 38147024, 2023). "In addition, we also observed that genes contributing to cancer cell stemness, such as CDKN3, BRIX1, TBCA, TMX2, and others, were highly expressed in the Luminal A DAB2IP-low tumors compared with the DAB2IP-high Luminal A tumors." (PMID 39418101, 2024). "Overall, the highest expression of TMX2 and the lowest expression of TMX3 was found in pan-cancer." (PMID 38147024, 2023). "Furthermore, we also investigated the correlation of TMX2 and TMX4 expression with immune-checkpoint-related stimulator genes in pan-cancer." (PMID 38147024, 2023).
neurological disorders (1 paper, 2022). "TMX2 has been identified as an important regulator in the developing brain and variants within the gene have been reported to cause severe neurological disorders, however, its role in headache or thyroid physiology is still unknown." (PMID 36672757, 2022).
TMX2 also shares sentences with these, for which no sentence is quoted: breast tumours (1 paper); Lissencephaly (1); neurodevelopmental disorder (1); viral infections (1).